GSTM1 (glutathione S-transferase mu 1)
Diseases named in the same sentence as GSTM1 in open-access papers (continued):
Sharing a sentence is not in itself a finding about the gene and the disease.
cardiomyopathy (5 papers, 2020 to 2025). A disease of the heart muscle or myocardium proper. "The GSTM1 null variant was more prevalent among cases with cardiomyopathy than controls (60.0% vs. 38.0%, p = 0.005): individuals with GSTM1 null genotype had 2.7-times greater risk of developing cardiomyopathy (p = 0.007) compared to those with GSTM1 positive genotype." (PMID 40413218, 2025). "A recent study carried out on 167 anthracycline-exposed childhood cancer survivors (75 cases and 92 matched controls with different diagnosis including 40 with bone tumors) reported that patients who had the GSTM1 null genotype had a significantly higher risk to develop cardiomyopathy." (PMID 32629971, 2020). "The authors conclude that also GSTM1 could be considered in a risk-prediction model to facilitate the identification of childhood cancer survivors who are at increased risk of anthracycline-related cardiomyopathy." (PMID 32629971, 2020). "Also, the ROS generation induces the expression of GSTM1 to cancel cellular oxidative stress caused by anthracycline exposure, which explains how the complete deletion of the GSTM1 gene (GSTM1 null variant) is associated with cardiomyopathy after anthracycline treatment." (PMID 40413218, 2025). "This was supported by evidence of downregulated GSTM1 expression in peripheral blood and in hiPSC-CMs of survivors with cardiomyopathy." (PMID 40362211, 2025). "Additionally, GSTM1 (rs36209093; DBP P = 9.94 × 10−15), encoding glutathione S-transferase Mu 1, has been implicated in cardiomyopathy resulting from iron overload." (PMID 38689001, 2024). "Moreover, they demonstrated a downregulation of GSTM1 gene expression in the peripheral blood as well as a reduced GSTM1 expression in human-induced pluripotent stem cell cardiomyocytes (hiPSC-CMs) generated from CCS who had anthracycline-related cardiomyopathy." (PMID 34638416, 2021).
cataract (5 papers, 2012 to 2026). Partial or complete opacity of the crystalline lens of one or both eyes that decreases visual acuity and eventually results in blindness. "However, recent studies showed that GSTM1 positive (GSTM1+/+) genotype was associated with a susceptibility to age-related cortical cataract in Asians, while GSTM1 or GSTT1 null genotype was associated with age-related cataract risk in Caucasians." (PMID 26208492, 2015). "We next investigated the effects of the profiles of GST genotypes on the risk of cataract, and examined the association between combinations of GSTM1 and GSTT1 null genotypes and cataract risk." (PMID 26208492, 2015). "Thus, this meta-analysis only evaluated the effects of GSTM1 and GSTT1 ploymorphisms on cataract risk." (PMID 26208492, 2015). "Our study suggests that the GSTM1 positive genotype and a combination of GSTM1 positive and GSTT1 null genotypes may be associated with a susceptibility to age-related cortical cataract in the Han Chinese population." (PMID 22665971, 2012).
liver disease (5 papers, 2016 to 2023). "Furthermore, our logistic regression analysis revealed significant association of null genotype of GSTM1 and rs4880TT of MnSOD with severity of liver diseases." (PMID 26937962, 2016). "So far, multiple genes have been shown to be associated with increased liver disease risk, such as CTLA-4, IL-18, transmembrane 6 superfamily member 2 and GSTM1." (PMID 34886817, 2021). "Notably, two previous studies evaluating the association of GSTM1 and GSTT1 polymorphisms with progression of liver disease in Egyptian and Taiwanese patients with chronic HCV showed considerably increased risk of advanced fibrosis in individuals with combined GSTM1/GSTT1 double-null genotype." (PMID 34451956, 2021).
non-small cell lung carcinoma (5 papers, 1999 to 2019). A group of at least three distinct histological types of lung cancer, including non-small cell squamous cell carcinoma, adenocarcinoma, and large cell carcinoma.
periodontitis (5 papers, 2014 to 2024). An acute or chronic inflammatory process that affects the tissues that surround and support the teeth. "Those with the GSTM1(+) genotype had a significant increase in periodontitis risk among smokers (OR = 3.1, 95%CI = 1.5–6.6) and a moderate risk increase among non-smokers (OR = 1.8, 95%CI = 1.0-3.1)." (PMID 38419025, 2024). "The patients with chronic periodontitis have a higher frequency of null and mutant polymorphisms in GSTM1, GSTT1, and GSTP1 compared with historical data from a healthy Mexican population." (PMID 27350970, 2014). "Comparing these data and our results using a population of 60 Mexicans with chronic periodontitis, an increase in the frequency of the GSTM1 null allele to 55% is observed and our data indicate that the GSTT1 null allele is present at a frequency of 65%." (PMID 27350970, 2014). "However, compared to historical data from a healthy Mexican population, periodontitis patients showed a higher frequency of null and mutant polymorphisms in GSTM1, T1, and P1." (PMID 38419025, 2024). "In conclusion, within the limitations of this study, the results suggest that compared with historical data from a healthy Mexican population, the population with chronic periodontitis shows an increase in null and mutant polymorphisms in GSTM1, GSTT1, and GSTP1." (PMID 27350970, 2014). "Their patients with chronic periodontitis had a higher frequency of null and mutant polymorphisms in the GSTM1, GSTT1 and GSTP1 genes as compared with the control Mexican population and it was concluded that the presence of these polymorphisms may be a risk factor for the development of CP." (PMID 36833382, 2023). "This study aimed to investigate the distribution of GSTM1, GSTT1, and GSTP1 variants and their roles in periodontitis susceptibility in a Caucasian population." (PMID 38419025, 2024). "The aim of this study was to determine the frequency of GSTM1, GSTT1, and GSTP1 polymorphisms in Mexicans with chronic periodontitis." (PMID 27350970, 2014). "This study aimed to determine the frequencies of GSTM1, T1, and P1 variants and analyze their role in periodontitis susceptibility in a Caucasian (Czech) population of non-smokers and smokers." (PMID 38419025, 2024). "Importantly, the results of this pilot study comprise the first report of the presence of GSTM1, GSTT1, and GSTP1 polymorphisms in a Mexican population with chronic periodontitis." (PMID 27350970, 2014). "There was found that periodontitis patients, particularly non-smokers, have altered oxidative stress responses due to GSTM1, GSTT1, and GSTP1 variations." (PMID 39599241, 2024). "Polymorphisms in the GSTT1 and GSTP1 genes were not significantly different between smokers and non-smokers; however, the GSTM1(+) genotype was significantly more frequent in smokers with periodontitis (p ≤ 0.05)." (PMID 38419025, 2024). "A better understanding of the function of the polymorphic genes GSTM1, GSTT1, and GSTP1 and a better understanding of the disease could contribute to the prevention of chronic periodontitis through personalized recommendations and specific intervention." (PMID 27350970, 2014). "A recent case-control study in a Pakistani population reported that the absence of GSTM1, the presence of GSTT1, and the mutant allele (G) at rs1695 in the GSTP1 gene may be associated with susceptibility to periodontitis." (PMID 38419025, 2024). "In an investigated set of 201 controls and 203 periodontitis patients, the researchers detected that the absence of GSTM1, presence of GSTT1, and mutant allele (G) at rs1695 in the GSTP1 gene might be associated to susceptibility to periodontitis." (PMID 38419025, 2024). "Therefore, the aim of this study was to determine the frequency of GSTM1, GSTT1, and GSTP1 polymorphisms in Mexican population of smokers and nonsmokers with chronic periodontitis." (PMID 27350970, 2014).
rectal cancer (5 papers, 2007 to 2020). A primary or metastatic malignant neoplasm that affects the rectum. "A study of 952 rectal cancer cases and 1205 controls in the United States found that a borderline significant interaction existed between the GSTM1 null allele and cigarette smoking." (PMID 17603900, 2007). "In addition, the GSTP1 rs1138272 polymorphism together with the GSTM1 (glutathione S-transferase M1) null genotype was reported to be associated with the risk of colon or rectal cancer in the Indian population." (PMID 30740061, 2018).
thyroid cancer (5 papers, 2007 to 2022). "The only three studies published so far on involvement of GSTT1 and GSTM1 null alleles in thyroid cancer risk were carried out in three different regions with different frequencies of GST deletion genotype in general population (Spain, Brazil and Portugal)." (PMID 18601742, 2008). "GSTT1 null showed 3.48 times higher risk of developing thyroid cancer (p < 0.0001) while GSTM1 null showed protective effect (p < 0.05, OR = 0.718)." (PMID 18601742, 2008). "GSTT1 null showed 3.48 times higher risk of developing thyroid cancer (p < 0.0001, 95% CI = 2.48–4.88) while GSTM1 null showed protective effect (p < 0.05, OR = 0.72, 95% CI = 0.52–0.99)." (PMID 18601742, 2008). "Although our findings, showed association between the GSTM1 null genotype with decreased risk against development of PTC (OR = 0.718, p < 0.05) comparing to control group, is consistent with previous reports with other cancers including thyroid cancer." (PMID 18601742, 2008). "Variations in GSTT1, GSTM1 and GSTP1 have been previously demonstrated to influence drug efficacy and toxicity and also to modify individual susceptibility to cancers however, there are scarce data specific to patients with thyroid cancer." (PMID 18601742, 2008). "The aim of the present study was to compare GSTM1 and GSTT1 gene frequencies between patients with benign and malignant tumors of the thyroid gland." (PMID 18094897, 2007). "Genes related to cytoprotection and antioxidant response (e.g., Gsta3, Gstm1, Nqo1, Gpx2), as well as the H2O2-producing gene Aox1 that is usually decreased in thyroid cancers, were all downregulated in thyroids of KO mice, as found previously in other tissues." (PMID 32961913, 2020).
breast tumor (4 papers, 2016 to 2021). "Of these, the top candidate was in the promoter of the GSTM1 gene and was associated with higher expression of GSTM1 in breast tumors." (PMID 27964748, 2016). "Simlarly, a regSNV in the promoter of GSTM1 gene, rs36208869, was predicted in our pipeline to increase ER binding and was shown to be highly correlated with the expression of GSTM1 whose higher levels in ER+ breast tumors are associated with a better survival." (PMID 27964748, 2016). "Interestingly, we examined the METABRIC and KM-Plotter datasets and found that higher expression of GSTM1 in breast tumors is associated with better survival of patients with ER+ tumors (logrank p value for METABRIC = 8.2E-4, logrank p value for KM-Plotter = 5.9E-3)." (PMID 27964748, 2016). "The carcinogen metabolism genes, GSTM1, GSTM2, and GSTM4 are also located in this region and our eQTL analysis of breast tumor revealed highly significant associations between rs17024629 and these genes." (PMID 34234117, 2021). "Furthermore, we observed a significant increase in the expression of GSTM1 and SOD2, two key enzymes related to ROS detoxification, in the basal-like breast tumours of overweight/obese patients compared to those of lean patients." (PMID 34073320, 2021).
colitis (4 papers, 2019 to 2024). Inflammation of the colon. "Meanwhile, broccoli sprouts and bok choy increased the expression of antioxidants such as Nrf2, NADH-Quinone oxidoreductase 1, Gstm1, Srxn1, and GPx2 to improve colitis symptoms." (PMID 38779039, 2024). "Western immunoblotting revealed that, while both RSV and C33 maintained high expression levels of Ho-1 in WT colitis mice, C33 induced higher expression of Gstm1, AKR1B8, and Nqo1 proteins than RSV (lanes 2 and 3)." (PMID 31885813, 2019). "We found that colitis significantly decreased GST classes alpha, mu, and pi (GSTA3, GSTM1, GSTP1)." (PMID 38668322, 2024).
diabetic retinopathy (4 papers, 2013 to 2017). "Hederagenin and lupeol interacted with GSTM1 to decrease the risk of diabetic retinopathy and nephropathy." (PMID 29051733, 2017). "The following genes had significant association with diabetic retinopathy: GSTM1 and VEGF and also VEGF had significant association with diabetic foot ulcer." (PMID 26587547, 2015). "Investigating null/positive genotype of GSTM1 in a study, which used ARMS-PCR for genotyping, revealed that null genotype is significantly associated with diabetic retinopathy (P < 0.05)." (PMID 26587547, 2015). "The relation between GSTT1 and GSTM1 and diabetic retinopathy has also been shown in Iranian population." (PMID 26587547, 2015).
endothelial dysfunction (4 papers, 2010 to 2025). In vascular diseases, endothelial dysfunction is a systemic pathological state of the endothelium (the inner lining of blood vessels) and can be broadly defined as an imbalance between vasodilating and vasoconstricting substances produced by (or acting on) the endothelium. "The null genotype for glutathione-S transferase M1 (GSTM1) had a modifying effect in the relationship between PM and AS, resulting in a more marked endothelial dysfunction (flow-mediated dilation) associated with PM exposure in T2D subjects." (PMID 40427454, 2025). "In addition, GSTM1 knockdown induced in vitro upregulation of cell adhesion molecules and markers of endothelial dysfunction, ICAM-1 and VCAM-1, which has also been confirmed in the clinical settings using plasma samples from patients with ESRD." (PMID 33574979, 2021). "The same polymorphism also modulates the association between PM and inflammation and endothelial dysfunction, as adhesion molecules, vascular cell adhesion molecule-1 (VCAM-1) and intercellular adhesion molecule-1 (ICAM-1) were particularly higher in subjects carrying the GSTM1 null gene." (PMID 40427454, 2025). "Given the pivotal role that oxidative stress plays in the development of endothelial dysfunction, we postulated that the lack of GSTM1 activity contributes to the formation of ROS and oxidative damage." (PMID 33574979, 2021). "Markers of endothelial dysfunction, ICAM-1 and VCAM-1, were both increased in ESRD patients lacking GSTM1, while ICAM-1 was upregulated in endothelial cells with a low level of GSTM1 exposed to uremic serum, further strengthening their potential biomarker role as predictors of CVD in ESRD patients." (PMID 33574979, 2021).
glioma (4 papers, 2010 to 2021). A benign or malignant brain and spinal cord tumor that arises from glial cells (astrocytes, oligodendrocytes, ependymal cells). "There were 13 publications that included 2,312 glioma patients and 4,966 healthy controls included in the publication analysis of the GSTM1 null/present variant and glioma risk." (PMID 31528233, 2019). "Deletion of GSTM1 has been shown to be associated with pediatric glioma." (PMID 34732244, 2021). "Therefore, the aim of this case-control study was to investigate the relationship between GSTP1 (Ile105Val and Ala114Val), GSTT1 (null/present) and GSTM1 (null/present) variants and the risk of glioma in the Han Chinese population compared with the Caucasian population." (PMID 31528233, 2019). "At this time, there have been several previously published and formally analyzed systematic reviews and meta-analysis of published studies on the GSTP1, GSTM1 and GSTT1 variants and the risk of primary brain tumors, including glioma 1, 2, 38-40." (PMID 31528233, 2019). "GSTP1 (Ile105Val and Ala114Val), GSTM1 (null/present) and GSTT1 (null/present) variants were genotyped in 384 glioma patients and 340 healthy controls." (PMID 31528233, 2019). "Another large-scale study obtained data indicating the absence of an association between polymorphisms of GSTM1 (Ins/Del), GSTM3 (A63С), GSTT1 (Ins/Del) and the development of gliomas, glioblastomas, and meningiomas." (PMID 22649665, 2010).
head and neck squamous cell carcinoma (4 papers, 2006 to 2022). A squamous cell carcinoma that arises from any of the following anatomic sites: lip and oral cavity, nasal cavity, paranasal sinuses, pharynx, larynx, and salivary glands. "This study aimed to identify GSTT1 and GSTM1 gene null genotypes in smokers with head and neck squamous cell carcinoma and to compare these frequencies with those seen in smokers without a history of cancer, to identify possible susceptibility biomarkers for head and neck cancer." (PMID 17221058, 2006). "Although many epidemiological studies have investigated the association between GSTM1 or GSTT1 null genotype and head and neck squamous cell carcinoma (HNSCC), the results remain conflicting." (PMID 23077643, 2012). "In this study we were unable to show a correlation between GSTM1 and GSTT1 genotypes and the development of head and neck squamous cell carcinomas in cigarette smokers." (PMID 17221058, 2006). "This study did not allow us to establish any correlation between GSTT1 and GSTM1 null genotypes and the development of head and neck squamous cell carcinoma in smokers." (PMID 17221058, 2006). "GSTM1 and GSTT1 null genotype frequencies were evaluated by multiplex PCR in 45 cigarette smokers with head and neck squamous cell carcinomas and 45 cigarette smokers without this disease." (PMID 17221058, 2006).
heart failure (4 papers, 2019 to 2025). Inability of the heart to pump blood at an adequate rate to meet tissue metabolic requirements. "Overexpressing GSTM1 alleviates post-MI fibrosis, offering a novel perspective for preventing heart failure." (PMID 40448227, 2025). "In human dilated cardiomyopathy (DCM) patients with severe heart failure, GSTM1 expression was decreased alongside aggravated fibrosis." (PMID 40448227, 2025). "In this study, Gsta1/4, Gstm1/2, and Gstp1GSTs all showed a significant upward trend, demonstrating that doxorubicin-induced heart failure has a strong correlation with oxidative stress." (PMID 33362553, 2020). "Future research may pave the way for the application of GSTM1-based therapy to prevent adverse ventricular remodeling and heart failure." (PMID 40448227, 2025). "Our findings indicate a significant downregulation of GSTM1 in mouse CFs after MI and in heart tissues from patients with DCM in advanced heart failure." (PMID 40448227, 2025). "Several studies have indicated that the absence of the Gstm1 gene might elevate the risk of developing T2DM and increase the susceptibility to kidney failure and heart failure." (PMID 39330516, 2024).